XBP1 (X-box binding protein 1)
Diseases named in the same sentence as XBP1 in open-access papers (continued):
Sharing a sentence is not in itself a finding about the gene and the disease.
prolymphocytic leukemia (1 paper, 2015). A mature B- or T- cell leukemia with progressive clinical course. "In cell lines, including a prolymphocytic leukemia cell line MEC1, both agents as well as thapsigargin induced robust ER stress response which included PERK phosphorylation, XBP1 splicing and CHOP induction, indicating that ER stress response is dysfunctional in CLL." (PMID 26606677, 2015).
small intestinal tumors (1 paper, 2025). "More importantly, we noted that aged Atg16l1/Xbp1/Rnaseh2bΔIEC mice spontaneously presented with nearly complete penetrance of small intestinal tumors (95.0%), when compared to Xbp1/Rnaseh2bΔIEC mice (61.7%)." (PMID 41057521, 2025).
tongue cancer (1 paper, 2023). A malignant neoplasm affecting the tongue. "Moreover, we detected increased AREG and bFGF protein levels in the blood of tongue cancer patients with X‐box binding protein‐1 (XBP1) activation in tumours under cytotoxic therapy and found that XBP1 activation is associated with poor prognosis of patients." (PMID 36639835, 2023).
Uterine leiomyoma (1 paper, 2023). The presence of a leiomyoma of the uterus. "The results of ChIP-seq and RNA-seq confirmed that BPA promoted the proliferation of uterine leiomyoma cells by acting on X-box binding protein 1 (XBP1) and downstream integrin subunit alpha 2 (ITGA2), thereby activating the PI3K/AKT signaling pathway." (PMID 38133401, 2023).
tumor (343 papers, 2006 to 2026). "The high demand for nutrients by rapidly proliferating tumor cells leads to deficiencies in essential metabolites such as glucose and amino acids, activating the IRE1α/XBP1 signaling pathway to promote lipid synthesis and ER expansion." (PMID 41407677, 2025). "Mouse embryonic fibroblasts (MEFs) deficient for XBP1 or PERK resulted in tumor growth inhibition due to augmented sensitivity to hypoxia when transplanted into mice." (PMID 41372991, 2025). "The accumulation of 4-Hydroxynonenal (4-HNE)-protein complexes in tumor-associated DCs further illustrates how oxidative stress can trigger DCs dysfunction through X-box Binding Protein 1 (XBP1) activation." (PMID 41035634, 2025). "The IRE1α-XBP1 pathway also polarizes tumor-associated macrophages (TAMs) via macrophage inducible Ca2+-dependent lectin receptor (Mincle)-dependent ER stress in an immunosuppressive pro-tumorigenic manner." (PMID 41301006, 2025). "A crucial and unexpected role of XBP1 has recently been uncovered in driving the dysfunction of tumor-associated dendritic cells (tDCs) within the tumor microenvironment." (PMID 40278350, 2025). "Strikingly, IRE1 silencing strongly attenuated AMO1 cell proliferation in vitro and caused a complete regression of pre-established AMO1 tumor xenografts in vivo, whereas XBP1 silencing had little effect in both settings." (PMID 40208872, 2025). "Increased LPO within DCs causes functional impairment and promotes tumor activity via a mechanistic link to the activation of the inositol-requiring enzyme 1 α-x-box binding protein 1 (IRE1α-XBP1) pathway, along with the accumulation of lipid peroxides." (PMID 41176596, 2025). "Another example of UPR-mediated lipid–immune cell crosstalk is the role of XBP1 in interfering with the homeostasis of tumor-associated dendritic cells." (PMID 41301006, 2025). "As was shown, either the deficiency of IRE1α or XBP1 in tumor cell prominently abrogated the role of HA15 in delaying the growth of B16F10 tumor." (PMID 38291473, 2024). "What’s more, we have conducted an evaluation of the number of regulatory T cells (Tregs) or the percentage of Granzyme B+ and IFN-γ+CD8+T cells in HA15-treated tumor harboring IRE1α or XBP1 deficiency using immunofluorescence staining analysis." (PMID 38291473, 2024). "In contrast, in mouse models of intestinal cancer, loss of XBP1 function contributes to tumour incidence." (PMID 38297380, 2024). "In summary, nivolumab can inhibit the metastasis and proliferation of NSCLC by inhibiting PD-L1 and regulating the IRE1α/XBP-1 signaling pathway in tumor-associated macrophages." (PMID 39189933, 2024). "Induces cytotoxic T lymphocytes (CTLs) to target specific tumor associated antigens such as highly over-expressed tumor antigens XBP1, CD138 and CS1." (PMID 37492478, 2023). "The accumulation of cholesterol in tumor-infiltrating CD8 T cells induced XBP-1 signaling, which was linked to increased expression of immune checkpoints and functional exhaustion of these T cells." (PMID 37744326, 2023). "Astragalin can increase reduced spleen and thymus indexes caused by Lewis cells and regulate XBP1-mediated endoplasmic reticulum stress response to regulate immunity and inhibit tumor growth." (PMID 38146464, 2023). "Some scholars believe that the upregulation of EsRβ can inhibit the expressions of IRE1 and XBP1, increase the sensitivity of tumor cells to tamoxifen, and cause the apoptosis of chemoresistant cells." (PMID 37790807, 2023). "Gene Set Enrichment Analysis (GSEA) confirmed that canonical XBP1-target genes were downregulated in both XBP1s-deficient and IRE1/XBP1-deficient tumor cDC1s." (PMID 37346037, 2023). "We conclude that XBP1 deletion in tumor-associated DCs tunes effector T cell responses independent of cross-presentation or canonical DC activation." (PMID 37346037, 2023).
tumor (continued). "inositol-requiring enzyme 1α (IRE1α)−X-Box Binding Protein 1 (XBP1) signaling, for example, promotes tumor immune evasion by enhancing the functions of tumor-associated myeloid cells." (PMID 36890838, 2023). "Simultaneously, apoptosis was increased in the Xbp1-deficient cells, thereby inhibiting tumor growth." (PMID 35402506, 2022). "High XBP1 levels were associated with advanced clinical stages, a high malignancy index, and a poor tumor necrosis rate in OS." (PMID 36303551, 2022). "XBP1s can partly protect the tumor from hypoxia, while deficiency of Xbp1 can hinder hypoxic tumor growth." (PMID 35402506, 2022). "In another report, sustained XBP1 activation was shown to impair antigen presentation by tumor-associated dendritic cells." (PMID 36139473, 2022). "In contrast, in tumor-associated DCs, XBP1 KO led to changes in lipid metabolism, which improved cross-presentation of tumor antigens and consequent anti-tumor T cell activity." (PMID 35446348, 2022). "Accumulation of lipids resulted in endoplasmic reticulum stress in tumor-associated DCs and led to expression of constitutive X-box binding protein 1 (XBP1), which disrupts lipid homeostasis in DCs." (PMID 35806328, 2022). "The IRE1α-XBP1 axis was also shown to be crucial in the tumor antigen cross-presentation of CD8α+ conventional DCs, and deficiency of XBP1 in CD8α+ DCs resulted in a defective phenotype and antigen-presenting capacity." (PMID 35884393, 2022). "In this tumor, XBP-1 gene signature is strongly associated with HIF-1α gene signature, and they correlate with a lower relapse-free survival." (PMID 33423689, 2021). "Regarding miR-199, previous data showed that this miRNA was associated with cell cycle processes in HCC via XBP1/cyclin D and acted as a tumor suppressor by targeting RGS17 in the inhibition of tumor growth." (PMID 32330203, 2020). "Targeted ablation of XBP1 in muscle ameliorates muscle loss in tumor-bearing mice, while its overexpression promotes atrophy of cultured myotubes." (PMID 32635462, 2020). "PERK and XBP1 are the most important ER membrane proteins that are recently linked to tumor cell migration/invasion processes such as ECM and EMT." (PMID 33014334, 2020). "During hypoxia-induced ER stress, IRE1-driven X-box-binding protein 1 splicing increases tumor cell tolerance to hypoxia, whereas loss of this protein impairs hypoxic tumor growth." (PMID 28134767, 2017). "These recent studies indicate that the sustained activation of the IRE1α-XBP1 arm of the UPR promotes immunosuppression in cancer hosts by modulating the activity of tumor-associated DC, neutrophils, and MDSCs." (PMID 28105371, 2017). "Other reports indicate that elevated levels of XBP1 in tumor-associated dendritic cells disrupt anti-tumor T-cell immunity through increased lipid peroxidation and lipid accumulation." (PMID 29113324, 2017). "It is also possible to regulate lipid levels in DC by targeting the MSR1 scavenger receptor that promotes lipid uptake or the IRE1α/XBP1 pathway that triggers triglyceride synthesis in tumor-associated DC." (PMID 29209327, 2017). "PERK and XBP1 are both important factors in tolerance of hypoxia; loss of expression of either factor inhibits tumor growth and increased apoptosis following hypoxia." (PMID 26810754, 2016). "Loss of XBP-1 severely inhibits tumor growth, demonstrating XBP-1 as an essential survival factor for solid tumors." (PMID 25426559, 2015). "Overexpression of XBP1 was significantly associated with advanced clinical stages, high degree of malignancy and low tumor necrosis rate." (PMID 26633383, 2015).
tumor (continued). "It has been demonstrated that XBP1-deficient tumor cell survival is reduced under hypoxic conditions in vitro, and these cells are unable to develop tumors in vivo." (PMID 26491226, 2015). "For example, XBP1-deficient cells are vulnerable to hypoxia-induced apoptosis, leading to the impairment of hypoxic growth in tumor xenografts." (PMID 25941664, 2015). "The IRE1α-XBP1 pathway is one of the most important ER-stress response pathways that are implicated in tumor growth, metastatic progression, and chemo-resistance." (PMID 26633383, 2015). "Modulating Xbp1 activity further influenced the growth of ISC/EE tumors that accumulate due to defective EB differentiation in Notch loss of function conditions: While spliced Xbp1 prevented tumor formation, loss of Xbp1 exacerbated the growth of these tumors." (PMID 25166757, 2014). "Notably, the IRE1α-XBP1 signaling pathway has also been linked to tumor progression and therapy resistance, in part through the positive regulation of IL-6 in several types of cancer, including hepatocellular carcinoma and melanoma." (PMID 40278350, 2025). "Moreover, the expression of the critical downstream mediator of IRE1α pathway, XBP1, was also highly associated with the mRNA levels of the indicators of lymphocytes and anti-tumor immunity, including PTPRC (encoding CD45), CD8A, GZMB and IFNG." (PMID 38291473, 2024). "Conversely, XBP1 deficiency enhanced T cell anti-tumor function and prolonged patient survival." (PMID 39080273, 2024). "While HA15 treatment led to substantially reduction of Foxp3+CD4+ Tregs in TME, either the deficiency of IRE1α or XBP1 in tumor cells could partially reverse this alteration." (PMID 38291473, 2024). "In TNBC, XBP1 is usually upregulated and linked to tumor development and a poor prognosis." (PMID 39777114, 2024). "Similarly, XBP1-mediated lipid peroxide accumulation in tumor-associated DCs can induce ER stress and inhibit antigen presentation function of DCs, thus indirectly hindering its anti-tumor effect." (PMID 37700339, 2023). "The discrepancies between double versus single knock-out models may be attributed to RIDD counteractivation in XBP1-deficient tumor cDC1s, which is a phenotype reported in XBP1-knock-out cDC1s in steady state." (PMID 37346037, 2023). "Additionally, hypoxic activates the expression levels of XBP1 mRNA and protein, and the deficiency of XBP1 inhibits tumor growth." (PMID 37854285, 2023). "On the other hand, XBP1 inhibits mitochondrial function in tumor-associated T cells." (PMID 36475773, 2023). "Interestingly, we found that XBP1 expression was significantly associated with the survival of some tumor patients after adjusting for clinical factors, including age, sex, race, stage and purity." (PMID 36092910, 2022). "Moreover, both BiP and XBP1 are implicated in sustaining tumor cell survival and in mediating the tumor cells’ response to glucose deprivation." (PMID 35992272, 2022). "Furthermore, they targeted Xbp1 in tumor-associated DCs using polyethylenimine-based nanoparticles encapsulating siRNA and demonstrated therapeutic efficacy in an in vivo tumor model." (PMID 35806328, 2022). "According to the clinicopathological analysis, the overexpression of XBP1s protein was significantly associated with NSCLC tumor stage and lymph node metastasis, and then we investigated the role of XBP1 in the progress of migration, invasion and metastasis of NSCLC." (PMID 34094948, 2021). "Hence, XBP1 deficiency in T cells restores anti-tumor capacity and delays malignant progression, resulting in the increased survival of mice with OvCa." (PMID 34356855, 2021). "We next investigated the contribution of XBP1 in TAMs associated with tumor growth and metastasis." (PMID 34667145, 2021).
tumor (continued). "This XBP1-HIF-1α-dependent signature is associated with tumor aggressiveness and poor prognosis." (PMID 33423689, 2021). "Although IRE-1α activation is frequently considered a positive process for the cell for exiting ER stress, recently, it was reported that constitutive activation of XBP1 in tumor-associated DCs inhibits the capacity of these cells to activate anti-tumor T cells." (PMID 35069537, 2021). "Earlier reports showed that XBP1 is required for the development and survival of BMDC and that the deletion of XBP1 in lymphoid dendritic cells or in tumor-associated dendritic cells improves antigen cross-priming and reduces tumor (ovarian) growth in the mouse." (PMID 32520957, 2020). "Elevated reactive oxygen species (ROS) in tumor‐associated DC also contribute to intracellular lipid peroxidation, leading to activation of the ER stress sensor XBP1 that in turn drives triglyceride biosynthesis and further accumulation of lipids that blunt Ag presentation." (PMID 32508018, 2020). "Tumor tissue can inhibit the uptake of glucose in T cells and cause defects in intracellular N-catenin glycosylation, which triggers the activation of IRE1α-XBP1." (PMID 33117713, 2020). "Interestingly, XBP1 can blunt antitumor activity by interfering with the function of tumor-associated dendritic cells." (PMID 30679434, 2019). "Interestingly, tumor-infiltrating DCs deficient in XBP1 acquire immunostimulatory and anti-tumoral characteristics in vivo." (PMID 30282948, 2018). "Likewise, targeted delivery of nanoparticles encapsulating siRNA has been used to silence in tumor-associated DC the expression of either XBP1 or the IRE1α endoribonuclease that cleaves Xbp1 mRNA into a form that encodes functional protein during ER stress." (PMID 29209327, 2017). "Interestingly, a recent study also showed that XBP1 can blunt the antitumor activity by interfering with the function of tumor-associated dendritic cells." (PMID 27303918, 2016). "High spliced XBP1 expression is associated with increased tumor growth and poor patient survival." (PMID 27668268, 2015). "Genetic variants in Xbp1 are associated with higher susceptibility to IBD and a recent study indicates that Xbp1 can act as a tumor suppressor in the intestinal epithelium, by limiting intestinal proliferative responses and tumor development through the control of local inflammation." (PMID 25945494, 2015). "Previous studies have implicated XBP-1 as an essential survival factor for ER stress and tumor growth, thus we chose whether miR-214 exert an opposite effect in HCC for further investigation." (PMID 22359598, 2012). "Furthermore, XBP-1 significantly correlates with LMP1 expression in NPC tumor biopsies, suggesting that XBP-1 can promote virus-associated cancer in a unique way by driving expression of a viral oncogene." (PMID 20398343, 2010). "These included tumor stage, two DNA features (loss of chr 17q and 22q segments), and eight RNA features (immature dendritic cell, T-follicular helper cell, XBP1, IgG, and HER2 amplification signatures, as well as three unsupervised RNA signatures labeled Unknown8, Red18, and Green7)." (PMID 40057511, 2025). "Activation of IRE1α–XBP1 has been shown to stimulate the release of cathepsins by macrophages in in vitro studies, thus promoting the invasion of cancer cells; this process can be blocked by inhibitors of IRE1α, reducing the tumor invasion caused by macrophages." (PMID 40035165, 2025). "Our present study has demonstrated that tumorous IRE1α significantly potentiated anti-tumor immunity in response to ER stress, which was highly associated with increased expression and secretion of pro-inflammatory cytokines and chemokines triggered by XBP1 and NF-κB downstream of IRE1α." (PMID 38291473, 2024).